INS (insulin)
Diseases named in the same sentence as INS in open-access papers (continued):
Sharing a sentence is not in itself a finding about the gene and the disease.
diabetes (continued). "In terms of diabetes and its complications, the regulation of FOXM1 can improve insulin resistance and insulin secretion and reduce the occurrence and development of diabetes." (PMID 37238726, 2023). "Type 2 diabetes mellitus (T2DM), the most prevalent kind of diabetes, is characterized by insulin resistance and insufficient insulin production." (PMID 38022046, 2023). "All admissions had type 2 diabetes, 64% an HbA1c > 53 mmol/mol (n = 57, 64%), 75.3% were prescribed oral anti-diabetes medication (including 16.9% SGLT2 Inhibitors) and 48.3% were prescribed insulin." (PMID 37858102, 2023). "We found that 2-AAA was significantly higher in PWH who have diabetes, than in PWH who were insulin sensitive or pre-diabetic." (PMID 37745703, 2023). "Elevated levels of insulin and IGF-1 also affect cancer prognosis, with worse outcomes in patients with diabetes and hyperinsulinemia." (PMID 37233716, 2023). "In type 1 diabetes mellitus (T1DM), the β cells of the pancreas are destroyed, which leads to an absolute insufficiency of insulin in the blood." (PMID 36512089, 2023). "Type 2 diabetes mellitus (T2DM) is characterized by hyperglycemia and hyperinsulinemia due to excess hepatic glucose production and insulin resistance." (PMID 37895834, 2023). "On the other hand, nutrition treatment is critical in the management of diabetes, and meal-planning strategies for T1DM place a strong emphasis on the relationship between meal insulin dosage selection and the expected amount of carbs consumed." (PMID 38111457, 2023). "As type 2 diabetes mellitus (T2DM) is a progressive disease, insulin therapy is ultimately required in its chronic management." (PMID 37132569, 2023). "Among those with cirrhosis and diabetes at baseline, we observed a higher rate of incident HCC among those who initiated insulin after developing cirrhosis." (PMID 38055642, 2023). "This study was designed to analyze the rate of β-cell death in different groups of diabetes mellitus (GDM, T1D and T2D) by two potential biomarkers (INS and Amylin)." (PMID 37264478, 2023). "Type 2 diabetes mellitus (T2DM) is a chronic complex metabolic disease with impaired insulin sensitivity and diminished insulin secretion." (PMID 36938283, 2023). "Continuous subcutaneous insulin infusion (CSII), especially in the pediatric population with diabetes, is widely used to achieve better dosing accuracy and flexibility in insulin regulation." (PMID 37232708, 2023). "Age, sex, BMI, diabetes duration, SBP, history of cardiovascular disease, presence of diabetic retinopathy, cigarette smoking, time since last meal, exogenous insulin use, and glycosylated hemoglobin." (PMID 37485272, 2023). "Type 2 diabetes mellitus (T2DM), a growing health problem worldwide, is a metabolic disorder characterized by hyperglycemia due to insulin resistance and defective insulin secretion by pancreatic β-cells." (PMID 37488560, 2023). "Similarly, many antibiotics (i.e. flucloxacillin, gentamicin, erythromycin, cefuroxime, dicloxacillin, meropenem and piperacillin) were adjusted with the co-medication insulin aspart, which may reflect the altered metabolic control during infection in patients with diabetes." (PMID 37676853, 2023). "Our findings regarding the function of PRSS8 on insulin secretion may add to an improved understanding of the pathophysiologic mechanisms underlying the development of diabetes and indicate the potential usefulness of targeting PRSS8 in the treatment of diabetes." (PMID 37277555, 2023). "Characterized as an acute complication of diabetes, DKA usually occurs in young patients with type 1 DM (T1DM) and used to be fatal in pre-insulin era." (PMID 37700304, 2023). "People suffering from diabetes experience abnormal blood glucose levels (BGL), mainly owing to the absence or unregulated production of insulin." (PMID 36992029, 2023).
diabetes (continued). "A large number of cohort studies have previously assessed the associations of metabolic phenotypes of obesity, defined by elevated levels of insulin or HOMA‐IR, with cardiovascular disease, diabetes, and several cancer types." (PMID 37096432, 2023). "Of the 297 (48.7%) with diabetes, 11 (3.7%) had type 1 diabetes mellitus, 268 (90.2%) had T2DM (122 (45.5%) insulin-treated), 12 (4.0%) had new-onset diabetes after transplant (NODAT), and 6 (2.0%) were classified as other." (PMID 37152098, 2023). "Metformin, a drug widely used to treat type 2 diabetes mellitus, has been shown to activate AMPK in the liver, thereby reducing gluconeogenesis and enhancing insulin sensitivity." (PMID 36674447, 2023). "Diabetes mellitus (DM) is a chronic metabolic disease characterized by the destruction of pancreatic β cells by the immune system, leading to impaired insulin secretion or reduced insulin sensitivity." (PMID 39698026, 2023). "Based on the high co-morbidity of diabetes and NAFLD and the pathways which connect these diseases, the impact of insulin treatment is also under investigation as potentially yielding NAFLD treatment benefits." (PMID 36902639, 2023). "Intensive insulin therapy is usually accompanied by daily SMBG and has proved to reduce the end-organ damage in patients with insulin-dependent diabetes mellitus." (PMID 37892937, 2023). "Patients with pharmacologically treated diabetes undergoing TKA show the highest rate of LOS > 4 days, while patients with insulin-treated diabetes show the highest rate of postoperative complications." (PMID 37430329, 2023). "First, we use an injectable insulin comparator, which like GLP-1 RAs is often used in more advanced diabetes stages, in Israel and other countries." (PMID 37244998, 2023). "The serum concentration of GPLD1 is directly proportional to total triglyceride, cholesterol, and insulin, implying a pivotal role for GPLD1 in triglyceride metabolism, insulin resistance, and the development of diabetes." (PMID 38085726, 2023). "This review outlines the rationale for how the physiologic secretion of insulin orchestrates glucose metabolism, and how mimicking this secretion profile may serve to improve glycemic control, reduce cellular inflammation, and potentially improve outcomes in patients with diabetes." (PMID 37446104, 2023). "“Prediabetes” was the most commonly used keyword in the literature, followed by “diabetes”, “type 2 diabetes”, “diabetes mellitus”, “insulin resistance”, “obesity”, “metabolic syndrome”, “HBA1C”, “IGT”, “IFG”, and “Insulin”." (PMID 36908460, 2023). "Subsequently, their anti-diabetic effects were analyzed in insulin-resistant HepG2 cells and in animals with STZ-induced diabetes." (PMID 37754257, 2023). "In conclusion, the improvement effect of RES on diabetes is related to the activation of SIRT1 and insulin-related signaling pathways, thereby inhibiting inflammation and oxidative stress, and improving mitochondrial function." (PMID 37009462, 2023). "Some researchers suggested that the increased risk of diabetes associated with elevated ALT levels may be related to decreased liver insulin sensitivity, while others proposed that the elevated ALT levels may be a consequence of IR in participants, and ALT, in turn, increased the risk of diabetes." (PMID 38089616, 2023). "Moreover, the type of diabetes could be divided by a more disciplined standard and the experiments could be carried out from a multiple perspective with endocrinology such as biochemical analysis, insulin resistance and so on." (PMID 36816302, 2023). "Data from the Diabetes Control and Complications Trial showed an increased risk of severe hypoglycaemia and excessive weight gain with intensive insulin therapy highlighting the necessity for interventions that achieve glycaemic control without reliance on large insulin doses." (PMID 37432920, 2023).
diabetes (continued). "In terms of diabetes compensation, repeated HBOT throughout the year reduces insulin consumption, recovers residual insulin secretion, and suppresses the release of contra-insular hormones such as glucagon, somatotropic hormone, and hydrocortisone." (PMID 37760247, 2023). "Elevated urinary C‐peptide to creatinine ratio (UCPCR) as an alternative measurement is shown to be related to insulin secretion dysfunction; however, data regarding UCPCR predictive value for CAD in diabetes mellitus (DM) are scarce." (PMID 36808709, 2023). "Hypoglycaemia is a harmful potential complication in people with type 1 diabetes mellitus (T1DM) and can be exacerbated in patients receiving treatment, such as insulin therapies, by the very interventions aiming to achieve optimal blood glucose levels." (PMID 37072364, 2023). "An impaired IGF pathway engenders insulin resistance or abnormal insulin/IGF response, which also leads to an enhanced metabolic syndrome manifestation such as diabetes, hyperglycemia, hyperlipidemia, and obesity." (PMID 36947108, 2023). "Our results suggest that by personalizing diabetes treatment through HDT enhances the time-in-range, reduces the hyper and hypo events, and more importantly, reduces insulin infusion showing its efficacy in managing diabetes." (PMID 36983097, 2023). "For diabetes treatment, patients chronically received metformin (97%), sulfonylurea (49%), DPP-4 inhibitors (10%), SGLT2 inhibitors (20%) and insulin (24%)." (PMID 37764998, 2023). "These additional cells produce adipokines to regulate carbohydrate metabolism and its sensitivity to insulin that finally favors inflammation and hyperglycemia processes, which involve an interconnection between dyslipidemia, obesity, diabetes mellitus (DM), oxidative stress, and inflammation." (PMID 37298303, 2023). "For controlling diabetes, she used neutral protamine Hagedorn (NPH) insulin [20 units every 12 hours, subcutaneous injection (SQ)] and regular insulin (12 units in the morning and 8 units at night, SQ)." (PMID 37496037, 2023). "The Diabetes Control and Complications Trial (DCCT) which randomized people with T1D to receive intensive or standard insulin therapy; after 21 months 216 of 817 subjects had already experienced a severe hypoglycemic episode." (PMID 37958696, 2023). "Type 2 diabetes mellitus (T2DM) is a heterogeneous group of disorders characterized by variable degrees of insulin resistance, impaired insulin secretion, and increased hepatic glucose production." (PMID 37954809, 2023). "The Diabetes Control and Complications Trial (DCCT) conducted a longitudinal clinical trial administering an intensive therapy that consisted of multiple daily insulin injections or an external insulin pump to maintain normoglycemic levels." (PMID 37822049, 2023). "Hyperglycemia in type 2 diabetes mellitus (T2DM) arises because of a combination of insulin resistance, inadequate production of insulin by the β cells of the pancreatic islets, and hyperglucagonemia." (PMID 37056543, 2023). "Type 2 Diabetes Mellitus (T2DM) is a form of DM whereby the tissue is resistant to insulin." (PMID 37818560, 2023). "In addition, the prevalence of taking β blockers, a cardioprotective drug that could worsen glycemic control by increasing insulin resistance and decreasing insulin release, also increased significantly, which contributed to the increasing prevalence of diabetes." (PMID 37213641, 2023). "Type 2 diabetes mellitus (T2DM) is characterized by pathophysiological abnormalities, including impaired insulin secretion from pancreatic islet β-cells, peripheral insulin resistance, and excessive glucose production by the liver." (PMID 37876013, 2023). "90% of all diabetes cases are type 2 diabetes mellitus (T2DM), which is characterized by impaired insulin secretion, insulin resistance, and obesity." (PMID 37701894, 2023).
diabetes (continued). "Type 2 DM (T2DM) or non-insulin-dependent diabetes mellitus (NIDDM); that is, the most prevalent form of DM; is primarily related to reduced insulin sensitivity and increased insulin resistance in peripheral tissues (American Diabetes Association, 2017)." (PMID 37346806, 2023). "Type 1 diabetes mellitus (T1DM) is results from insufficient insulin secretion by islets; its treatment requires lifelong use of insulin injections, which leads to a large economic burden on patients." (PMID 37965322, 2023). "Among the diabetes-related signaling molecules, PPAR-γ (a transcription factor) helps to regulate lipid and glucose metabolism, enhancing insulin sensitivity." (PMID 37298440, 2023). "Diabetes mellitus (DM) is a serious metabolic disorder characterized by chronic hyperglycemia with impaired metabolism of carbohydrate, fat, and protein resulting from a defect in insulin secretion or insulin action." (PMID 36782199, 2023). "Moreover, insulin treatment could reverse these effects of diabetes." (PMID 37396950, 2023). "More than 90% of cases of diabetes mellitus are T2DM, which is distinguished by tissue insulin resistance (IR), an insufficient compensatory insulin secretory response, and insufficient insulin production by pancreatic islet cells." (PMID 37764820, 2023). "This study showed that longer duration of diabetes (5–10 years or >10 years) was associated significantly with poor glycemic control and this is possibly explained by the progressive impairment in insulin secretion that will eventually end by pancreatic failure with increasing DM duration." (PMID 37008178, 2023). "Meanwhile, KEGG pathway analysis exhibited that the DEGs were significantly enriched in the insulin signaling pathway, AGE-RAGE signaling pathway, and type 2 diabetes mellitus." (PMID 37943808, 2023). "Type 2 diabetes mellitus (T2DM) is a progressive condition that results from insulin resistance and progressive impairment of insulin secretion." (PMID 37264625, 2023). "Glycaemic control of Type 1 Diabetes Mellitus (T1DM) remains a challenge due to hypoglycaemic episodes and the burden of insulin self-management." (PMID 37759290, 2023). "Insulin/IGF signaling is reported to be dysregulated in obesity, diabetes, and breast cancer underscoring intricate overlaps in the underlying metabolic abnormalities and disease spectrum." (PMID 37511200, 2023). "Regarding diabetes, while hepatic CYP1A1 and CYP2E1 activity and lipid peroxidation (LPO) were enhanced in STZ-induced diabetic rats, insulin treatment attenuated the enzyme activities and LPO levels." (PMID 37428327, 2023). "In STZ-induced diabetic Wistar rats, myricetin decreases DPP-4 activity, its expression, and diabetes-induced NLRP3 inflammasome activation, increasing circulating GLP-1 and insulin levels." (PMID 37305094, 2023). "For AD, the main component of amyloid plaques is a specific βA, which is formed as a result of the targeted proteolysis of the APP, and, for diabetes, it is amylin (or islet amyloid polypeptide; IAPP), as well as insulin." (PMID 37833898, 2023). "Type 2 diabetes mellitus (T2DM), which is characterized by two important pathophysiological characteristics, namely β-cell dysfunction and impaired insulin responsiveness in insulin target tissues, will affect 95% of all diabetes cases." (PMID 38202777, 2023). "Furthermore, the loss of body weight in diabetes results from the degradation and catabolism of fats and proteins, and it is attributed to increased utilization of the body energy reserves accompanied by the absence of the regulatory hormone insulin." (PMID 37215365, 2023). "For example, using insulin in Type 2 diabetes might be associated with a longer duration of the disease and a higher risk of diabetes complications; however, patients in our study may not be able to afford insulin or were not receiving insulin for the appropriate reasons." (PMID 39035064, 2023).
diabetes (continued). "More than 90% of diabetes is T2DM, which is a chronic metabolic disease, manifested by high glucose levels induced by insulin resistance, defects in insulin secretion, or inadequate compensatory insulin secretory response." (PMID 37223013, 2023). "In our review, only three studies used a GLP1-RA medication in combination with another drug for diabetes: an SGLT2 inhibitor, biguanide, or insulin therapy." (PMID 37090383, 2023). "Another study in a small sample (n=34) of predominantly White (85%) adults with T1D and T2D using insulin demonstrated that the telehealth CGM initiation, delivered by a diabetes educator, was feasible and improved A1C and diabetes distress." (PMID 36761197, 2023). "The most common treatment patterns of type 2 diabetes mellitus included the use of metformin monotherapy, followed by the combination of metformin + DPP4 inhibitor or metformin + DPP4 inhibitor + insulin, and the use of a DPP4 inhibitor + insulin." (PMID 37403118, 2023). "A multicenter RCT compared the effects of transient intensive insulin therapy (continuous subcutaneous insulin infusion [CSII] or multiple daily injections [MDI]) vs. oral antidiabetic agents on β-cell function and diabetes remission." (PMID 37468901, 2023). "Type 2 diabetes mellitus (T2DM) is a metabolic disorder characterized by chronic hyperglycemia, insulin resistance, and insufficient insulin secretion." (PMID 37305094, 2023). "Insulin is typically administered through injections and is the preferred medication for treating HIV-related diabetes." (PMID 37746464, 2023). "A recent study has proposed that inhibition of the KATP channels by mutation or long-term use of sulfonylureas leads to persistently depolarised β-cells in diabetes and that GLP-1R switches coupling from Gs-to-Gq signalling to amplify insulin secretion." (PMID 36943057, 2023). "As people living with diabetes are using CGM systems in order to manage their CHO intake and insulin doses, the correct handling of CGM devices and data is essential." (PMID 37568982, 2023). "When insulin is available, children in LMIC often get conventional insulin treatment in an inconsistent manner in contrast to developed countries where intensive diabetes treatment is offered." (PMID 37033222, 2023). "A total of 872 people with insulin-requiring diabetes were recruited and consented to participate in ECHO Diabetes across 2 recruitment phases in the summer and winter of 2021 across the states of California (n=495) and Florida (n=377)." (PMID 37535407, 2023). "This knowledge should encourage further investigations into beneficial, promising therapeutic approaches, regarding central insulin sensitivity and GLUT4 expression, to fight diabetes- and Alzheimer-related neurodegeneration." (PMID 38003671, 2023). "To this end, we analysed data from longitudinal OGTTs performed in adult and youth participants in the Diabetes Prevention Trial–Type 1 (DPT-1), using previously validated models that provide estimates of both beta cell function and insulin sensitivity." (PMID 36459177, 2023). "Hypoglycemia has a major impact on patient health and glycemic management during insulin therapy for both type 1 (T1DM) and type 2 diabetes mellitus (T2DM)." (PMID 36974247, 2023). "Compared with patients without DKD or DR, those with DKD or DR both had older age, longer duration of diabetes, higher SBP, more frequent hypertension history, a higher proportion of ever insulin use, higher UACR, and lower eGFR." (PMID 37096235, 2023). "These insights strengthen one's knowledge of insulin secretion physiology and set forth the TRPC3 channel as an appealing candidate for drug development in the treatment of diabetes." (PMID 36642838, 2023). "Also, diabetes mellitus (DM) is a group of metabolic diseases characterized by hyperglycemia resulting from defects in insulin secretion, insulin action, or both." (PMID 37445852, 2023).